CIP2A (cellular inhibitor of PP2A)
Diseases named in the same sentence as CIP2A in open-access papers (continued):
Sharing a sentence is not in itself a finding about the gene and the disease.
cancer (continued). "First the product of KIAA1524 gene CIP2A is a proto-oncoprotein and second, CIP2A is overexpressed at high frequency (40-80%) in most of the human cancer types (as discussed in this review)." (PMID 25015035, 2014). "At the same time, we focused on the mechanism of AKT phosphorylation to further investigate how CIP2A is involved in the PI3K/AKT/mTOR pathway, which is critical to cancer progression." (PMID 25109354, 2014). "Stabilizing PP2A and thus rendering CIP2A non-functional is a significant avenue to cancer therapies." (PMID 41155727, 2025). "Though the core mechanism behind CIP2A inhibitors appears to be through the inhibition of CIP2A transcription rather than its binding to PP2A, the overall effect of increasing PP2A activity in cancer cells is still comparable to the SET inhibitors." (PMID 38184584, 2024). "In cancers, the best characterized endogenous inhibitors of PP2A are SET and CIP2A." (PMID 38542160, 2024). "CIP2A protein can be degraded through both the UPS and the lysosomal pathway in cancer." (PMID 39399646, 2024). "Though CIP2A is also one of the known endogenous inhibitors of PP2A, a great deal is still being discovered into the way it functions as an oncogene and prevents the activation of PP2A in cancer." (PMID 38184584, 2024). "Frequency of anti-CIP2A/p90 and the TAA panel in cancer patients and normal controls." (PMID 36911405, 2023). "The CIP2A–TOPBP1 complex tethers fragmented chromosomes from micronuclei for asymmetric mitotic inheritance, explaining distinct patterns of chromosome rearrangements in cancers and genomic disorders." (PMID 37165191, 2023). "As the inhibition of CIP2A may allow for the PP2A-mediated proteolytic degradation of c-Myc in cancer cells and thereby limit the cancer cells’ growth and transformation, the CIP2A may be a promising candidate for targeted treatment." (PMID 37048102, 2023). "Although the specific mechanism of CIP2A transcription suppression is yet to be reported, this is of great interest as CIP2A repression and subsequent upregulation of PP2A activity in key cancer-promoting pathways (such as Akt and c-myc) affects the sensitivity of these solid tumors to bortezomib." (PMID 37763671, 2023). "Next, we discuss cancer progression induced in various organs by SET and CIP2A." (PMID 37097392, 2023). "Thus, the aberrant PP2A inhibition by SET/CIP2A and ERK hyperactivation by oncogenes coexist in many clinical cancer cases." (PMID 36463234, 2022). "CIP2A is an oncoprotein proved to be upregulated in a variety of peripheral tumors, and promotes tumor cell growth through inhibiting the dephosphorylation of PP2A substrates which are involved in cancer development." (PMID 35286657, 2022). "In addition to SET, cancerous inhibitor of PP2A (CIP2A), another well-known cellular inhibitor of PP2A, is often overexpressed in various cancer tissues." (PMID 34244560, 2021). "Although these direct inhibitions are present in some cancers, PP2A is more commonly inactivated by upregulation of endogenous PP2A inhibitors: protein SET (also known as inhibitor 2 of PP2A) and cancerous inhibitor of phosphatase 2A (CIP2A)." (PMID 34129940, 2021). "Additionally, CIP2A mRNA and protein content is regulated by MYC, creating a positive feedback loop between the two oncogenes in cancer." (PMID 32110991, 2020). "There are several methods published on indirectly activating PP2A as an anti-cancer treatment, such as antagonizing the endogenous PP2A inhibitors SET (via OP449 or FTY720), and CIP2A (via bortezomib, erlotinib, or celastrol) or disrupting PP2A post translational modifications." (PMID 33322239, 2020).
cancer (continued). "CIP2A mediated inhibition of PP2A impairs its crucial role in tumour suppression, as it can no longer inactivate numerous kinase-driven intracellular signalling pathways that allow cancer progression." (PMID 31623614, 2019). "Endogenous protein inhibitors of PP2A, SET and CIP2A, were up-regulated in various human cancers, so it is vital to review the essential mechanisms of tumor promotion by the okadaic acid class compounds, together with cancer progression by SET and CIP2A in humans." (PMID 30341686, 2018). "Knockdown of CIP2A was an effective way to improve EVE sensitivity and might be useful to develop novel cancer treatments." (PMID 29805747, 2018). "In addition to CIP2A, SET nuclear proto-oncogene (SET) oncoprotein is another intrinsic inhibitor of PP2A, participating in cancer progression." (PMID 30154367, 2018). "The identification of the common B′-binding motif in CIP2A reveals an important mechanism of CIP2A to compete with substrate binding in inhibition of the normal function PP2A-B′ holoenzymes and stimulation of cancer cell signaling." (PMID 28884018, 2017). "In contrast to the observed survival, the weighted average of expected 5 year survival rate was higher for CIP2A high/KRAS mutant than for CIP2A low/KRAS mutant patient group, suggesting that high CIP2A expression is an indicator of poor prognosis in KRAS mutant cancers." (PMID 26278961, 2015). "As well, mutation of pRb but not p130 occurs frequently in nearly all human cancers, which explains to a certain extent why degradation of pRb but not p130 is necessary in upregulating CIP2A level." (PMID 25650660, 2015). "To study whether relationship between Oct4 and CIP2A also exists in other cancers than TCs, we set to study patient derived HNSCC cell lines for CIP2A and Oct4 protein and mRNA expression." (PMID 25474139, 2015). "Our data could have two impacts, CIP2A can be a candidate biomarker for cancer diagnosis and CIP2A has novel function in JNK signaling pathway in cancer progression." (PMID 26560124, 2015). "Moreover, our recent evidences that CIP2A regulated cell proliferation through AKT/PKB signaling pathway, and promoting cancer metabolism enriched the network being played by CIP2A." (PMID 26560124, 2015). "According to our studies, we found the possible interaction between CIP2A and AKT signaling pathway, which may help to reveal the mechanism for CIP2A-promoted cancer progression." (PMID 25109354, 2014). "In contrast to the variable expression in cancer cells, normal stromal tissue in the adjacent areas of cancer did not stain with CIP2A." (PMID 22537901, 2012). "Our data shows that evolutionary conserved CpG islands at the proximal CIP2A promoter are not methylated both in normal and cancer cells." (PMID 21445343, 2011). "Since CIP2A has also been reported as an ELK1 target in ovarian, uterine cancer, and liver cancer, its inhibition by erlotinib provided a new mechanistic approach which could be applicable in more cancer types." (PMID 40862737, 2025). "In addition to prevention of colorectal adenoma by green tea catechins, it is worthwhile to study whether green tea catechins inhibit overexpression of SET and CIP2A along with PP2A activity in cancer cells, as suitable targets for cancer prevention." (PMID 37097392, 2023). "Also, bortezomib, a US Food and Drug Administration (FDA)-approved proteasome inhibitor, was able to reduce CIP2A expression levels in several cancer cell lines, although the mechanism of action is not elucidated yet." (PMID 31214504, 2019). "However, all these results showed that CIP2A function is not conserved across different cancer cell types." (PMID 27144172, 2016). "On the other hand, these results give important guidelines to estimate potential immunological side-effects of future CIP2A targeted cancer therapies, which probably would not be as limiting with comparison to reported effects of many existing cancer treatments." (PMID 27100879, 2016).
cancer (continued). "Although CIP2A is not secreted into the extracellular space nor present as membrane-bound form, it is possible that immune response was initiated when nascent cancer cell was recognized by the immune system and lysed to release intracellular proteins, which induce autoantibody generation." (PMID 26560124, 2015). "However, whether the interplay between CIP2A and phospho-AKT plays a role in cancer progression, and how CIP2A facilitates AKT-mediated resistance to chemotherapy, remains unresolved." (PMID 25109354, 2014). "Furthermore, the mechanisms of CIP2A activation and overexpression in cancer cells has been investigated by several other studies in which E2F1, ETS1, and ATF2 were found to directly bind to the CIP2A promoter and further stimulate CIP2A transcription." (PMID 24884612, 2014). "We examined CIP2A protein expression in various cancer and noncancer cell lines." (PMID 23342256, 2012). "Furthermore, these results strongly suggest that SNPs on CIP2A promoter do not significantly contribute to CIP2A overexpression in cancer." (PMID 21445343, 2011). "However, both others and we have shown that CIP2A knockdown does not affect cancer cell migration or invasion through matrigel." (PMID 21445343, 2011). "Role of CIP2A in promoting expression of stemness markers and proliferation of spermatogonial progenitor cells, together with our data that CIP2A is a novel Oct4 regulated gene, suggests that CIP2A might also be expressed in cancer stem cell like cells, however this has not been studied as yet." (PMID 25474139, 2015). "However, the cancer type does not account for the survival effect of CIP2A." (PMID 26278961, 2015). "However, whether CIP2A could be a new drug target for cancers is not fully investigated, and the anti-tumor activity of CIP2A-targeting agents remains largely unknown." (PMID 21655278, 2011). "However, we found that CIP2A inhibition by shRNA and small compounds inhibited OXPHOS and prompted NSCLC cells to undergo glycolysis through dephosphorylation of PKM2 pS287, indicating that cancer cells might undergo metabolic reprograming in response to therapeutic stress." (PMID 38321019, 2024). "Although CIP2A inhibitors are not as advanced in clinical trials as LB100, their potential in cancer therapy through PP2A modulation is being actively researched." (PMID 38999976, 2024). "In cancer, the non-genomic inhibition of PP2A activity by elevated expression of endogenous PP2A inhibitor proteins (PAIPs), such as CIP2A, SET, PME1, ARPP19 and TIPRL, greatly exceeds the frequency of genetic mutations on PP2A genes." (PMID 31717978, 2019). "Oct4 and CIP2A co-expression with MYC in TCs was also very obvious and only two cancer samples were MYC negative." (PMID 25474139, 2015). "Finally, demonstration that CIP2A expression can be systematically inhibited without severe consequences to normal mouse development and viability may have clinical relevance regarding targeting of oncogenic CIP2A for future cancer therapies." (PMID 22461891, 2012). "Moreover, demonstration that CIP2A expression can be systematically inhibited without severe consequences to normal mouse development and viability may have clinical relevance regarding targeting of oncogenic CIP2A for future cancer therapies." (PMID 22461891, 2012).
tumor (120 papers, 2010 to 2025). "Consistent with its oncogenic properties, CIP2A also plays a tumor-promoting role in GC, although the underlying molecular mechanisms remain incompletely understood." (PMID 41155583, 2025). "Fourth, mutation of only one amino acid from the N-terminal head of CIP2A was sufficient to abrogate tumour growth of aggressive TNBC cell line." (PMID 36854761, 2023). "Mechanistically, the robust tumor-promoting effects of CIP2A overexpression have been linked to inactivate protein phosphatase 2A (PP2A)." (PMID 37470692, 2023). "Still, low CIP2A expression level was associated with better treatment response, defined by tumor regression grade, after long‐course (C)RT." (PMID 29441695, 2018). "Further investigation of lapatinib-mediated CIP2A regulation will advance our understanding of lapatinib-associated anti-tumor activities and drug resistance." (PMID 28938602, 2017). "Second, lapatinib inhibited xenograft tumor growth in vivo in association with CIP2A downregulation." (PMID 26824320, 2016). "An association appeared between high CIP2A expression and high histological tumour grade (P=0.009), and invasion depth >4 mm (χ2-test, P=0.041)." (PMID 21610708, 2011). "We found an association between high CIP2A expression and high grade, tumour invasion depth >4 mm, and high proliferation index." (PMID 21610708, 2011). "CIP2A is related to a poor patient prognosis and may be applied as a prognosis biomarker in evaluating the risk of tumour metastasis." (PMID 29893470, 2018). "Evidence has suggested that CIP2A was associated with proliferation and apoptosis of tumor." (PMID 26894380, 2016). "Interestingly, however, they found that high nuclear expression was associated with prolonged OS suggesting that CIP2A functions are also tumor type specific." (PMID 25663244, 2015). "Clinically these results suggest that diagnostic evaluation of HNSCC tumors for Oct4 or Oct4/CIP2A positivity might help to predict HNSCC tumor radioresistancy." (PMID 25474139, 2015). "Importantly, tamoxifen inhibited in vivo xenograft tumor growth in association with CIP2A downregulation." (PMID 25228280, 2014). "In loss of function studies, CIP2A depletion has been shown to reduce the overall tumor xenograft size in nude mice, and to impair clonogenicity and anchorage-independent growth of tumor cells." (PMID 21445343, 2011). "When the tumor specimens were stratified according to their clinically relevant Gleason scores as low risk and high risk tumors, there were significantly more CIP2A-positive cases among tumors with Gleason scores of 7-10 compared to those with Gleason scores of 6 or less (p < 0.001)." (PMID 20964854, 2010). "Meta-analysis demonstrated that the associations between the expression of CIP2A and the prognosis were detected for overall survival (HR = 1.98, 95%CI = 1.69‐2.32), disease-specific survival (HR = 1.72, 95%CI = 1.50‐1.97), and time to tumor progression (pooled HR = 1.95, 95%CI = 1.56‐2.43)." (PMID 31534561, 2019). "Regarding tumor grading, the high CIP2A expression group was predominantly composed of moderately differentiated tumors (80.0%) and contained no well-differentiated cases." (PMID 40943297, 2025). "Collectively, our findings support a mechanism through which UCHL1 promotes tumor progression by modulating the CIP2A-c-Myc-cyclin signaling cascade." (PMID 41155583, 2025). "Through these interactions, CIP2A plays a pivotal role in the regulation of tumor-promoting signaling networks." (PMID 41155583, 2025). "CIP2A, a known oncoprotein overexpressed in multiple malignancies, modulates multiple oncogenic signaling pathways driving tumor growth and progression." (PMID 41155583, 2025). "We showed that CD-3 activates PP2A by inhibiting CIP2A and produces tumor growth inhibitory effects by promoting dephosphorylation of oncogenic AKT/mTOR signaling proteins in SCSC cells and xenograft tumors in a PP2A-dependent manner." (PMID 39850502, 2025).
tumor (continued). "Given the increasing clinical utility of liquid biopsies, it will also be useful to study the expression of CIP2A in circulating tumour cells, and its gene expression in total RNA (from whole blood) as well as circulating-free RNA." (PMID 40594400, 2025). "The overexpression of the cancerous inhibitor of protein phosphatase 2A (CIP2A) is related to resistance and tumor formation." (PMID 40900835, 2025). "By inhibiting PP2A, CIP2A activates oncogenic signaling pathways, thereby enhancing tumor growth and progression." (PMID 41362702, 2025). "We also provide evidence for overexpression of CIP2A in metastatic patients when compared to primary tumour samples indicating its potential involvement as an oncoprotein in the progression of the disease." (PMID 40594400, 2025). "Erlotinib, a food and drug administration (FDA)-approved EGFR kinase inhibitor for treating EGFR-mutant NSCLC, can reduce CIP2A levels, which indirectly restores the tumor-suppressive activity of PP2A." (PMID 41155727, 2025). "Although PP2A normally acts as a tumor suppressor by dephosphorylating c-Myc, CIP2A maintains c-Myc phosphorylation and promotes its overexpression by binding PP2A and inhibiting its activity, which ultimately drives tumor growth." (PMID 41155583, 2025). "Cancerous inhibitor of protein phosphatase 2A (CIP2A) is an oncoprotein promoting tumor progression via multiple pathways." (PMID 40943297, 2025). "IL-10 enhances tumor growth and metastasis by upregulating CIP2A expression via the PI3K signaling pathway." (PMID 38273373, 2024). "We found that in tumor tissues isolated from mice treated with celastrol alone or celastrol/2-DG, CIP2A and PKM2 pS287 were substantially decreased." (PMID 38321019, 2024). "Clinically, CIP2A level in tumor tissues was positively correlated with the level of phosphorylated PKM2 S287." (PMID 38321019, 2024). "Sequencing of the transformed clones revealed increased expression of several oncogenes (including CCNE2, CDC25A and CIP2A) and decreased expression of tumour suppressors providing a rationale for the observed cellular transformation." (PMID 39237765, 2024). "The expression of CIP2A/p90 in various tumor cells is regulated by other regulation factors with a certain complexity and cell specificity." (PMID 36911405, 2023). "CIP2A mRNA expression negatively correlated with autophagy gene expression in tumor tissues from HNC patients, showing, for the first time, its implication in a transcriptional autophagic context." (PMID 37925449, 2023). "Together, the discovered two-headed strategy by which CIP2A both disrupts functionality of the PP2A-B56α tumour suppressor complex, and simultaneously is itself protected from degradation, is likely to explain notable potency of CIP2A as a human oncoprotein." (PMID 36854761, 2023). "Proteins encoded by PP2A genes identified to be highly correlating with aggressive PDAC in GSE62165 were also significantly different between normal tissue and PDAC tumor, with again CIP2A, TIPRL and STRN as top altered hits." (PMID 37170215, 2023). "Polyphyllin I also decreased tumor volume and CIP2A, phospho-Akt, and vimentin expression in a xenograft murine model." (PMID 37568716, 2023). "CIP2A is overexpressed in human tumor entities including CRC, gastric cancer, head and neck squamous cell carcinoma, breast cancer, prostate cancer, and lymphoma." (PMID 33078202, 2021). "Higher levels of CIP2A are associated with a higher degree of PP2A inhibition and are known to confer treatment resistance in a wide range of other tumours." (PMID 33947031, 2021). "By preventing PP2A-B56α interaction with MYC, CIP2A gained scientific attention, and it is now considered a promising target for tumor treatment, particularly in AML, where it is overexpressed and promotes cell growth and neoplastic transformation." (PMID 32110991, 2020). "The average tumor volumes and weights in the CIP2A-shRNA group had also prominently decreased compared to those in the control group." (PMID 32321509, 2020).